STAT3 (signal transducer and activator of transcription 3)
Diseases named in the same sentence as STAT3 in open-access papers (continued):
Sharing a sentence is not in itself a finding about the gene and the disease.
cancer (continued). "The second-generation derivatives of many of these original hits had activity equivalent to or up to 3-fold greater than their parent compound in cancer cell growth-inhibition assays, but the increase in STAT3-inhibitory potency did not always correlate to the anti-proliferative capacity." (PMID 27027445, 2016). "Moreover, targeting the STAT3-Col XVII pathway-mediated suspension survival of TICs may help develop new strategies for preventing tumorigenicity and treating cancer." (PMID 27306323, 2016). "However, since there are no STAT3 targeting drugs in clinical trials beyond Phase II, the development of more potent and selective compounds that target STAT3 in cancer cells is still needed." (PMID 26883202, 2016). "Growth and survival of B-Raf(V600E) cancers is driven by B-Raf(V600E)-activated MAPK, as well as by a variety of de-repressed RTKs and transduction pathways that resist B-Raf(V600E) kinase inhibitors, including ErbB members, IGF1R, c-Met, IRS/PI3K/Akt/mTORC1, C-Raf/MEK/MAPK, Jak/STAT3 and/or c-Src." (PMID 26959890, 2016). "Considering that we have previously shown that MDA-9/Syntenin can activate STAT-3 in cancer cells, we postulate that lack of mda-9/syntenin in our mda-9−/− mice may abrogate STAT-3-mediated IL-17 production." (PMID 27341128, 2016). "It's reported that Cu-I exerts antitumorigenic activity by a ROS-mediated mechanism without inhibiting STAT3,18, 23 suggesting targeting the redox homeostasis may be an alternative mechanism of action for Cu-I in killing the cancer cells." (PMID 26890145, 2016). "In the present study we sought to test: 1) whether GRIM-19 is involved in high glucose (HG) induced altered cell metabolism in both cancer and cardiac cells, 2) whether GRIM-19/STAT3 signaling pathway plays a role in HG induced biological effects, especially whether AMPK activity could be involved." (PMID 27101310, 2016). "Interestingly, recent studies have also reported that leptin signaling may be involved in the promotion of CSC phenotype and that inhibition of STAT3 suppresses leptin-induced CSC activity and cancer progression in diet-induced obese rats." (PMID 26556856, 2016). "Moreover, SC09 inhibits transcriptional modularity of STAT3 but not another nuclear transcription factor NF-κB although both cross-talk in some cancers." (PMID 27705908, 2016). "However, inconsistently with previous studies in cancer cells, we did not observe the downregulation of STAT3 acetylation after STAT3-HDAC3 complex formation in human primary chondrocytes in response to leptin." (PMID 26636769, 2015). "Therefore, targeting STAT3 may provide a means to reverse the EMT phenotypes and prevent cancer invasion and metastasis." (PMID 26631279, 2015). "Given that the STAT3-related pathway is constitutively activated in diverse cancers, and acts as a potent pro-survival and anti-apoptotic signaling protein, these data demonstrated that NIPBL silencing inhibited cell growth, possibly via downregulating STAT3 and STAT3 target genes in NSCLC cells." (PMID 25963978, 2015). "Which kinase or kinases are responsible for mitochondrial STAT3 S727 phosphorylation in cardiac myocytes is undefined, although the ERK pathway was found to be necessary for S727 phosphorylation of mitochondrial STAT3 and Ras-mediated transformation in human cancer cells." (PMID 26664907, 2015). "Interestingly, the expression of gp130, total and phospho-STAT3 was similar in both cancer stem cells and non-stem cells." (PMID 26287605, 2015).
cancer (continued). "As the overall cellular role of MDSCs in cancer cells has not been fully established, targeting of molecule that activates STAT3 instead of using chemotherapeutic agents against MDSCs could constitute a better approach to cancer treatment." (PMID 25075523, 2014). "Thus, the anti-cancer potential of BBMD3 on GBM stem-like cells was not a result of inhibiting the STAT3 signaling pathway." (PMID 24732116, 2014). "In cancer cell lines, miR-146b was not induced following cytokine-induced STAT3 activation." (PMID 24762632, 2014). "However, to our knowledge, none of those direct STAT3 inhibitors (several of which were successfully tested in pre-clinical research) are currently in translational clinical studies for the treatment of cancer patients." (PMID 25268165, 2014). "Therefore, a potential anti-cancer drug candidate should selectively inhibit STAT3 function as a transcription activator while not affecting STAT1 (and other STAT family members)." (PMID 23950841, 2013). "Although our study shows that STAT3 is persistently activated in some, but not all of B cells in human cancers, the subset of B cells with activated STAT3 might be sufficient to potentiate and maintain persistent STAT3 activation in tumors." (PMID 23734190, 2013). "Both the NF-κB/IL6/JAK2/STAT3 cascade, which we show here is modulated by miR-221/222-mediated downregulation of ADIPOR1, and ZEB2 expression, which we have previously shown is repressed by TRPS1, are well-characterized effector pathways in cancer metastasis, invasion, and EMT." (PMID 23776679, 2013). "Interestingly, these compounds have little effect in cells in which STAT3 is not activated, pointing to STAT3 as a highly valid target to focus on for the design of anti-cancer compounds." (PMID 22423663, 2012). "While activation of signal transducer and activator of transcription 3 confers modest protection against SFN-induced apoptosis, mitochondria-derived reactive oxygen species (ROS) provide initial signal for apoptosis commitment in cancer cells exposed to this agent." (PMID 22970326, 2012). "We highlight differential expression of STAT3/HIF1 α and C/EBPβ in the CD33+ and CD11b+ subsets, respectively, that may aid other investigators in therapeutic targeting, subset expansion, or MDSC monitoring in cancer patients." (PMID 21658270, 2011). "The fact that Stat3 is only activated by low-affinity receptors in every cell type that we examined suggests that in vivo concentrations of EGFR ligands can stimulate low-affinity receptors and identifies a possible role for low-affinity receptors in the in vivo signaling of cancer cells." (PMID 21264347, 2011). "In the past several years, cucurbitacins have become a subject of intense investigation because this triterpene family induces cancer cell death and many of them inhibit the phosphorylation of Janus kinase 2 (JAK2) and signal transducer and activator of transcription 3 (STAT3)." (PMID 21304528, 2011). "Recent evidences suggest the anti-cancer effects of BA, anti-inflammatory and anti-viral activities via various signaling pathways such as epidermal growth factor receptor (EGFR), hedgehog, signal transducer and activator of transcription 3 (STAT3) and nuclear factor-kappa B (NF-κB)." (PMID 21731766, 2011). "FLLL32 with higher concentration (10 μM) also inhibited the phosphorylation of STAT3 at residue Ser727 in SW480 cancer cell line but in HCT116 cancer cell line, the phosphorylation of STAT3 (Ser 727) could not be detected." (PMID 20712901, 2010). "In addition to Jak2/Stat3 pathway, PI3-K/Akt and MEK/Erk could also contribute to the regulation of IL-6 autocrine production in cancer cells." (PMID 21122157, 2010). "In contrast to the conserved STAT3 TFBSs, we could not detect STAT3 binding to the non-conserved STAT3 TFBSs in human cancer cell lines." (PMID 19730699, 2009).
cancer (continued). "To determine whether or not STAT-Finder is useful in identifying novel STAT3 target genes, we applied this program to a group of genes that are over-expressed in human cancer cells." (PMID 19730699, 2009). "Furthermore, a small molecule inhibitor that targets JAK/Stat3, JSI-124, also more selectively induced cleavage of caspase 3 in HeLa and SiHa cancer cell lines than Ishikawa cell line, which has low expression of elevated levels of Stat3 phosphorylation (Tyr705)." (PMID 17311011, 2007). "In that JAKs play an essential role in driving oncogenic Stat3 signalling, the ability of 15d-PGJ2 to downmodulate IL-6/JAK signalling may also in part, explain the antineoplastic properties of this agent against other types of human cancer." (PMID 15316561, 2004). "Furthermore, relationship between JAB1 and STAT3 related to tumorigenesis deserve further exploration and may reinforce the understanding of their regulatory mechanism by U-STAT3 and JAB1 which result in the development of effective cancer therapy." (PMID 40725945, 2025). "Interestingly, the role of STAT3 in cancer is not restricted to CML." (PMID 40697388, 2025). "In contrast, abrupt involution, typical of short or absent lactation, induces STAT3 activation, collagen remodeling, immune infiltration, and Notch signaling pathway activation, hallmarks of a pro-tumorigenic environment associated with TNBC and basal-like cancers." (PMID 41011846, 2025). "Hence, our findings elucidate a new mechanism underlying PD-L1 up-regulation, which is controlled by the activated p-STAT3/HLF/TFEB axis and provides a molecular basis for improving the clinical response rate and efficacy of targeted therapy and PD-1/PD-L1 blockade therapy in patients with cancer." (PMID 40779629, 2025). "Interestingly, another anti-inflammatory agent like curcumin that targets STAT3 and NFkB, namely celecoxib, may also provide anti-cancer effects, if not immune modulatory effects." (PMID 38539487, 2024). "However, human CRP induced both the expression of PD‐L1 and the activation of STAT3 in mouse bone marrow‐derived macrophages, similar to HMDMs (data not shown); therefore, validated animal models are needed to study the biological functions of CRP in various diseases, including cancer." (PMID 39564003, 2024). "Such approaches may not be entirely successful in cancer therapy because in addition to its canonical nuclear activity in gene regulation, STAT3 has non-canonical functions by regulating cellular respiration, energy production, and reactive oxygen species levels in the mitochondria." (PMID 39200368, 2024). "Notably, after knocking down STAT6 in macrophages, the expression of CD206 stimulated by IL-4 was not reduced by 23-HBA, and 23-HBA failed to inhibit the activation of the IL-10/STAT3/Bcl-2 signaling pathway induced by M2 macrophages and the resulting resistance to 5-FU in cancer cells." (PMID 38554148, 2024). "Moreover, the p-AMPK and p-STAT3 levels and VEGF expression were also reduced in TAMs of IDH2-deficient mice, indicating that most IDH2-deficient TAMs did not differentiate into M2 macrophages and that cancer progression was inhibited in IDH2-deficient mice." (PMID 39256649, 2024). "We then asked if STAT3 de-phosphorylation by 5-AZA could correlate with the upregulation of SOCS3 and/or PTPN6, as the former is a JAK/STAT inhibitor and the latter is a tyrosine phosphatase whose promoter methylation has been shown to contribute to STAT3 activation in other cancers." (PMID 38534772, 2024).
cancer (continued). "Importantly, chronic systemic STAT3 activation may also promote malignant transformation, which is of concern because RIC is a systemic phenomenon that may through STAT3 activation also promote cancer." (PMID 37620559, 2023). "The expression of p-CDK1, p-STAT3, CD44, and Sox2 was increased by gemcitabine, while fisetin could reverse the upregulation of these proteins in the combination therapy group, suggesting that inhibition of cancer stemness-related proteins by fisetin enhanced the effects of gemcitabine." (PMID 37743465, 2023). "However, none of the STAT3 inhibitors have yet been approved for cancer therapy." (PMID 37240202, 2023). "The signal transducer and activator of transcription 3 (STAT3), a transcription factor of tyrosine phosphorylation located at 17q21.2 with a length of 4899 bp, can be activated by cytokines and nonreceptor tyrosine kinases, participating in cancer cell proliferation, metastasis, and invasion." (PMID 37628777, 2023). "Moreover, the anti-cancer potential of apigenin is confirmed through its ability to modulate various cell signalling pathways, including tumor suppressor genes, angiogenesis, apoptosis, cell cycle, inflammation, apoptosis, PI3K/AKT, NF-κB, MAPK/ERK and STAT3 pathways." (PMID 36144783, 2022). "Furthermore, the anti-cancer effects of capsaicin have been demonstrated by the inhibition of Epidermal Growth Factor Receptor (EGFR) and PI3K/Akt/mTOR signaling pathways, and through IL-6/Signal Transducer and Activator of Transcription- 3 (STAT-3)/Cyclin D1 (CCND1) and survivin pathways." (PMID 35600864, 2022). "Since early STAT3 activation was regulated by fibronectin-JAK2, and its long-term activation was maintained by the cytoplasmic LMO2-LDB1 complex, phosphorylation of STAT3 on the cells cultured on polymer X might play an important role in regulating cancer stem-like properties in these cells." (PMID 36359204, 2022). "However, to date, no STAT3 inhibitor has been approved for cancer therapy." (PMID 35843865, 2022). "In this context, it is noteworthy that, in addition to cancer cells, CRC samples include fractions of additional cell types (e.g., immune cells and stromal cells) that could express variable levels of Smad7 and/or Stat3 mRNA, thus contributing to the RNA transcripts measured in such samples." (PMID 36291778, 2022). "However, STAT3 activators and their roles in different cancers are not fully understood." (PMID 36551576, 2022). "Furthermore, several factors have been identified for their crucial role in stimulating cancer-related inflammation, including cytokines (interleukins, TNF-α, TGF-β, and granulocyte macrophage colony-stimulating factor), chemokines, and transcription factors (NF-kB, STAT3, HIF-1-α)." (PMID 35956766, 2022). "It has been reported that inhibition of the MAPK pathway activates the JAK2/STAT3 pathway, and autocrine Interleukin 6 (IL-6) secretion and subsequent JAK2/ STAT3 activation may represent an unexpected route to overcome targeted inhibition of the MAPK pathway in BRAF mutant cancers." (PMID 36430869, 2022). "Interestingly, miR-145-5p hampers the proliferation of non-metastatic cancer cells by suppressing the activation of signal transducer and activator of transcription 3 (STAT3), suggesting that the status of STAT3 activation can switch the function of miR-145-5p in cancer." (PMID 33435156, 2021). "Although inhibiting the IL-17A/STAT3 pathway may allow control of tissue fibrosis, molecular targeting drugs for IL-17A, such as secukinumab and iexkizumab, are expensive and have not been used for malignant tumors." (PMID 32488650, 2021).
cancer (continued). "Therefore, it is possible that the phosphorylation level of STAT3 may have a negative modulatory effect on NK cells cytotoxicity and release of cytokines in patients with cancers." (PMID 34759824, 2021). "Our study uncovers a distinctive facet of tumorigenesis by identifying a previously unknown positive-feedback loop in the STAT3–TINCR–EGFR signaling pathway; this suggests that the feedback loop could represent a new therapeutic target in pharmacological strategies developed for human cancers." (PMID 33446634, 2021). "Hence, the suppression of the IL-6/STAT3 signalling pathway by cryptolepine, as well as inflammation, suggest that cryptolepine could be exploited as a cheaper and novel anti-cancer agent in the management of HCC and other cancers." (PMID 34078370, 2021). "Thus, our model that pSTAT promotes cancer development and uSTAT suppresses tumors by influencing heterochromatin dynamics can reconcile the contradicting results reported by different groups regarding the functions of STAT proteins, especially STAT3, in cancers." (PMID 32087696, 2020). "However, the JNK or JAK2 inhibitor could neither augment the anti-cancer effects of pKAL on STAT3 activity, nor on the expressions of CD44, Oct 3/4, β-catenin, and MMP-9 of RT-R-MDA-MB-231 cells." (PMID 32326231, 2020). "Interestingly, β-caryophyllene (50–100 μM) was found able to inhibit the activation of STAT3 along with the oxidative stress and DNA damage induced by the anticancer drug doxorubicin and by a condensed smoke from 3R4F cigarettes in both cancer and noncancerous cells." (PMID 33081075, 2020). "Moreover, several cytokines and factors can activate the STAT3 signaling pathway in cancer cells; thus, targeting only one of these elements may not be sufficient to suppress STAT3‐mediated oncogenic activity." (PMID 31246342, 2019). "In particular, DNA strand-breaking, activation of protein phosphatase 2C, abrogation of STAT3 signaling and the PI3K/Akt/mTOR pathway, transformation of mitochondria and uncoupling of oxidative phosphorylation, as well as inhibition of SIRT may account for cytotoxic and anti-cancer properties of GA." (PMID 31379572, 2019). "Interleukin (IL)-6 drives many of the cancer ‘hallmarks’ through downstream activation of the Janus kinase/signal transducer and activator of transcription 3 (JAK/STAT3) signaling pathway, we wanted to find whether STAT3 plays a role in IL-6-induced MMP2 and MMP9 expression." (PMID 31409371, 2019). "Furthermore, TAMs can facilitate cancer cell migration by activating EMT, for example upon release of lipocalin-2 (LCN2), TNF-α, IL-8, IL-6, and TGF-β1, which operate via activation of different EMT-promoting molecular pathways (e.g., Gas6/Axl-NF-κB, JAK2/STAT3/Snail, and PI3K/Akt)." (PMID 30200242, 2018). "However, in UC cells, we observed neither diminished phosphorylation nor decreased expression of STAT3, again indicating that the mechanisms mediating cellular effects may differ between cancer entities." (PMID 29312470, 2018). "Therefore, our results suggest that both regulatory macrophages and dexa-tolDC might be triggering similar tolerogenic mechanisms, probably through the STAT3 and Wnt5a signaling pathway, as its interaction with CD163 has already been reported in cancer studies." (PMID 30297862, 2018). "Some factors identified (e.g., NF-κB, STAT3, FOS) are known to be involved for transformation in our model, others (e.g., CEBPB, HIF1a, ETS2, FHL2, TCF7L2, and NFE2L2) have been described as oncogenes in other settings, and some proteins (BHLHE40 and MAFB) have not been well linked to cancer." (PMID 29802342, 2018). "Moreover, USP17 promoter region analysis revealed different transcription factor binding sites, including those for transcription factors HIF-1, STAT3, STAT6, and NF-κB, which are known to be activated on stimulating cancer cells by cytokines in a cross talk between TAMs and cancer cells." (PMID 30038267, 2018).